INS (insulin)
Diseases named in the same sentence as INS in open-access papers (continued):
Sharing a sentence is not in itself a finding about the gene and the disease.
Insulin resistance (continued). "Insulin signaling in insulin target tissues is also weakened by the burden of glucose toxicity, which leads to the aggravation of insulin resistance." (PMID 33807522, 2021). "We generated PRSs including several genetic variants to evaluate changes in insulin secretion (PRSIS), insulin resistance (PRSIR), and incident T2D in the prospective METSIM study including a total of 76 genetic variants increasing the risk of T2D." (PMID 34677406, 2021). "Based on our results, 8 weeks HFD decreases the insulin secretion by pancreatic cells as well as the induction of insulin resistance by target tissues." (PMID 34795728, 2021). "Elevation of circulating BCAA concentrations is associated with insulin resistance, onset of type 2 diabetes and cardiovascular events, and mitochondrial dysfunction, and BCAA concentrations are decreased with weight loss and insulin sensitization." (PMID 34083573, 2021). "Our results highlight the potential of high-dose ω-3PUFA supplementation as a mediator of increased insulin sensitivity in subjects with obesity, insulin resistance and elevated biomarkers of plasma and AT inflammation." (PMID 33753887, 2021). "In the present study, we analyzed the effect of phospholipid derivatives of selected natural aromatic acids on insulin action and their potential use to overcome insulin resistance." (PMID 34684619, 2021). "A study of the metabolic effects of bladder cancer in 22 patients and 10 controls reported a lower glucose clearance accompanied by higher insulin levels, which indicated a state of insulin resistance." (PMID 35127507, 2021). "Lifestyle interventions that improve body habitus alter biomarkers of insulin and insulin resistance, which are mechanistic contributors to breast cancer pathogenesis." (PMID 34578984, 2021). "In the severe insulin resistance state conferred by functional leptin deficiency, C57BL/6J are able to compensate for hyperglycemia with increased insulin production, whereas C57BLKS/J develops progressive hyperglycemia with islet atrophy." (PMID 33435282, 2021). "The main mechanisms involved in the pathogenesis and progression of the DKD in young people are insulin resistance and impaired insulin secretion." (PMID 34830194, 2021). "Subsequently, NRVMs were treated with insulin to induce the cardiomyocyte model of insulin resistance." (PMID 33547878, 2021). "Insulin resistance is a pathological condition in which target tissues fail to respond to insulin stimulation, leading to hyperglycemia and compensative hyperinsulinemia." (PMID 33467677, 2021). "Insulin resistance plays a prominent role in pathophysiology of type 2 diabetes and is characterized by diminished activity of insulin to regulate nutrient metabolism in target tissues, including liver, skeletal muscle, and adipose." (PMID 34073781, 2021). "Liver damage results in poor insulin clearance, which contributes to elevated systemic insulin and hyperinsulinaemia-induced insulin resistance." (PMID 33466498, 2021). "A recent study showed that upon glucose stimulation or HFD-feeding, CRL4COP1 E3 ligase can promote ETV5 degradation in pancreatic islet cells, thus mediating insulin over-secretion and promote insulin resistance and obesity." (PMID 34716308, 2021). "A combination of insufficient β-cell-derived insulin and peripheral tissue insulin resistance both play a role in the development of the disease." (PMID 34489979, 2021). "Conversely, sustained moderate physical activity increases basal metabolic rate and maximal oxygen uptake, which in the long term, increases metabolic efficiency and capacity, which reduces circulating insulin levels and insulin resistance." (PMID 33946913, 2021). "As revealed by this comprehensive review of numerous aspects of IDE biology, with an emphasis on its role in the regulation of insulin secretion and insulin resistance, the biology of IDE has proven to be considerably more complex." (PMID 33477364, 2021).
Insulin resistance (continued). "MS induces glycemia, hyperinsulinemia, and insulin resistance following interfering with insulin secretion and insulin sensitivity." (PMID 33995940, 2021). "Insulin resistance causes a disruption in the phosphoinositide-3 kinase (PI3-K/Akt) signalling pathway, which results in insufficient tissue insulin sensitivity." (PMID 33804680, 2021). "Sustained hyperglycemia triggers insulin resistance by impairment of the insulin signal transduction pathway, resulting in cardiovascular events such as myocardial injury." (PMID 34830501, 2021). "Swertiamarin attenuated HFD-induced weight gain, glucose intolerance, oxidative stress, and insulin resistance, and enhanced insulin signalling in mice." (PMID 33794740, 2021). "Insulin resistance is defined as the failure of many cells to respond to insulin hormone, to mediate insulin signaling and to take up glucose, thereby leading to abnormally high blood sugar levels known as hyperglycemia." (PMID 34768967, 2021). "Instead, this miRNA has been shown to contribute to insulin resistance and repression of insulin-stimulated glucose uptake in animal-models." (PMID 33911114, 2021). "In rats, resistin induces insulin resistance, but its effects on insulin sensitivity remain controversial in humans." (PMID 34037093, 2021). "Chronic hyperglycemia and hyperinsulinemia result in impaired insulin signaling in intact aortic valve tissue and includes features of insulin resistance." (PMID 34203572, 2021). "Although the three treatments decreased plasma glucose levels in our model of obese arthritic mice, only HCQ had a beneficial effect lowering the levels of insulin and, thus, reducing insulin resistance." (PMID 34721412, 2021). "By limiting the peripheral use of glucose with consequent hyperglycemia, insulin resistance determines compensatory increased levels of insulin in plasma." (PMID 34575946, 2021). "Impaired insulin secretion and insulin resistance are the two major mechanisms in the pathophysiology of T2D." (PMID 34677406, 2021). "Regarding insulin resistance in burned patients, previous studies have affirmed an improvement in insulin sensitivity as an indirect effect of β blocker administration, via the reduction of ERS and the mitigation of UPR." (PMID 34575946, 2021). "Early intensive insulin therapy has been reported to delay or even partially restore the development of type 2 diabetes mellitus by improving insulin resistance (IR)." (PMID 34917687, 2021). "Taking into account insulin pathway and insulin resistance, one gene which gathered our attention was G6PC3 (fold change expression of MHNW = 1.00, MUNW = 0.31, MHOW = 1.10, MUOW = 0.79)." (PMID 33669862, 2021). "Insulin resistance is commonly initiated due to a reduced sensitivity to insulin-mediated glucose clearance and an inability to produce glucose by liver enzymes." (PMID 34827338, 2021). "Hepatic fibrosis has also been shown to lead to reduced insulin clearance, insulin resistance, and T2D." (PMID 34497507, 2021). "It has been reported that four weeks of supplementation with broccoli (10 g/d) decreases serum insulin concentrations and homeostatic model assessment of insulin resistance (HOMA-IR) in individuals with T2D." (PMID 34579020, 2021). "Insulin plays a role in oxidative stress, not only through its signaling networks, but also in insulin resistance." (PMID 34829566, 2021). "Among them, glucocorticoids and especially prednisone, help glycemic control by inhibiting insulin synthesis, increasing insulin resistance, and stimulating gluconeogenesis." (PMID 34199977, 2021). "Strikingly, the improvement in insulin sensitivity was significantly more pronounced in the group of individuals with the lowest baseline insulin sensitivity, suggesting the potential for hypoxia therapy in people with severe insulin resistance." (PMID 34158069, 2021).
Insulin resistance (continued). "Participants with a greater degree of insulin resistance displayed a higher postprandial TG response than individuals who were more insulin sensitive, a finding previously observed in studies with healthy and obese individuals." (PMID 34544430, 2021). "Insulin resistance, a condition in which responders are insensitive to insulin, is mainly found in insulin-sensitive tissues such as liver, muscle and adipose tissue." (PMID 34948750, 2021). "T2D is characterized by excessive hepatic glucose production, a decrease in insulin secretion, and insulin resistance." (PMID 33800673, 2021). "TNF-α and IL-6 are involved in the disruption of insulin signalling and the further stimulation of gene expression related to insulin resistance." (PMID 34658643, 2021). "Smad 3-/- mice showed enhanced insulin sensitivity and reduced obesity, insulin resistance, and hepatic steatosis." (PMID 34345212, 2021). "Mitochondrial dysfunction is closely related to insulin resistance, and improving mitochondrial function has been shown to enhance insulin sensitivity." (PMID 34356628, 2021). "In parallel, an in vitro study showed that these exosomes can induce aging-related insulin resistance and inhibit insulin signaling activation in 3T3-L1 adipocytes, C2C12 cardiomyocytes, and primary cultured hepatocytes." (PMID 34016950, 2021). "Two studies examined this directly using hyperinsulinemic euglycemic clamps, finding improvement in both whole-body insulin sensitivity and peripheral insulin resistance in those adolescents taking metformin." (PMID 33828529, 2021). "This interaction between IGF-1 and insulin signaling pathways has an important role in hyperglycemia/insulin resistance–induced cardiac hypertrophy and fibrosis in the diabetic heart." (PMID 34205870, 2021). "VitD in this study was found to be significantly correlated (p < 0.05) with fasting insulin, fasting glucose, fasting C-peptide and insulin resistance indices (HOMA2-IR C-peptide)." (PMID 34380489, 2021). "The impaired insulin signaling cascade activation and impaired Glut-4 function is the primary defect in skeletal insulin resistance." (PMID 34684891, 2021). "Type 2 Diabetes Mellites (T2DM) is one of the major chronic non-communicable diseases and a metabolic disorder that occurs owing to insulin resistance and the subsequent failure to secrete sufficient insulin by the pancreas." (PMID 35155528, 2021). "In 111 obese women aged 36.73 ± 7.2 years, we measured changes in weight, lipid profiles, glucose, insulin, Homeostatic Model Assessment-Insulin Resistance Index (HOMA-IR), uric acid, aminotransferases, and irisin." (PMID 32892317, 2021). "Only the LCD group significantly reduced their glucose and insulin levels, and subsequently the homeostatic model assessment of insulin resistance index (HOMA-IR) index." (PMID 33806775, 2021). "Studies have shown impaired glucose homeostasis, high insulin levels, and insulin resistance for at least 4-5 weeks after the burn." (PMID 34405148, 2021). "For many years, aspirin has also been shown to attenuate insulin resistance and improve insulin secretion and signaling by decreasing nitric oxide-induced oxidative stress and reducing the levels of pro-inflammatory cytokines." (PMID 34575050, 2021). "The expressions of TNF-α and AKT, which were well known to be insulin resistance-related factors in adipocytes, were evaluated to observe the mechanistic effect for the insulin sensitivity by L. plantarum extracts." (PMID 33954196, 2021). "Individuals with high values along the first principal component (PC1) generally had high triglycerides and low HDL, indicating dyslipidemia, and higher levels of fasting blood glucose and insulin, indicating insulin resistance." (PMID 34006628, 2021). "High uric acid (UA) is demonstrated to directly inhibit insulin signaling by insulin receptor modification and induce insulin resistance." (PMID 34698101, 2021).
Insulin resistance (continued). "Tumor necrosis factor (TNF) is a multifunctional cytokine that can directly damage islet β-cells and induce insulin resistance by inhibiting the transduction of insulin signals." (PMID 34824300, 2021). "Furthermore, increased total fat and trunk fat are associated with insulin resistance, and therefore, lower total fat and trunk fat likely contribute to the relationship between higher dietary fibre intakes and lower fasting glucose, fasting insulin and HOMA2‐IR." (PMID 34585852, 2021). "Insulin resistance (or low insulin sensitivity) in skeletal muscle is a key feature of the pre-diabetic state and a predictor of type 2 diabetes (T2D)." (PMID 33639916, 2021). "Insulin resistance, as a pathophysiological precursor of type 2 diabetes, is defined as a reduced sensitivity to the action of insulin." (PMID 33882064, 2021). "These primary effects of TZDs markedly ameliorate insulin resistance, decreasing insulin requirement and positively impact on the features of the metabolic syndrome." (PMID 34440727, 2021). "In response to insulin resistance, pancreatic β-cells compensate by increasing insulin secretion characterized by hyperglycemia and hyperinsulinemia or normal insulinemia." (PMID 34673835, 2021). "Insulin resistance is the reduced ability of target cells (hepatocytes, adipocytes and skeletal myocytes) to elicit a glucose lowering response to insulin." (PMID 34680372, 2021). "The development of hepatic insulin resistance results in the inability of insulin to inhibit gluconeogenesis and an increase in de novo lipogenesis." (PMID 34357017, 2021). "The inhibition of endogenous miR-125b contributes to increasing insulin sensitivity in insulin resistance conditions." (PMID 34199293, 2021). "Further studies using tissue-specific PTP1B KO animals revealed that despite improved glucose homeostasis and insulin signaling in muscle and liver, these animals gained weight and developed insulin resistance when they were subjected to a high-fat diet." (PMID 34726241, 2021). "Maternal fasting glucose, insulin, homeostatic model assessment of insulin resistance (HOMA-IR), leptin, TNF-alpha, C-reactive protein, adiponectin, and lipids are measured by trained staff at each research site, following the established protocols." (PMID 33827659, 2021). "The elevated blood insulin in insulin resistance drives dyslipidemia, high blood pressure, and glucose metabolism alteration." (PMID 34299261, 2021). "According to literature data, increased amount of TNFα indicates macrophage-induced insulin resistance of the skeletal muscle, cerebral insulin resistance in Alzheimer’s disease and it inhibits the effect of insulin on glucose uptake and storage." (PMID 34572059, 2021). "In this study, although the testosterone level of the metformin group decreased, the dose of insulin injection was reduced, and the blood glucose of the two groups were similar, indicating that the level of insulin resistance still improved." (PMID 35002984, 2021). "Insulin resistance, a defect in insulin-mediated control of glucose metabolism in different tissues, prominently in muscle, adipose tissue, and liver, is one of the earliest manifestations of T2D and CVD." (PMID 34677406, 2021). "Insulin resistance (IR), caused by obesity and T2DM, results in poor insulin function in glucose uptake, metabolism, and storage." (PMID 33671428, 2021). "Measures of insulin resistance; fasting plasma insulin and homeostasis model of assessment for insulin resistance (HOMA-IR) were positively correlated with serum visfatin, resistin and fetuin-A." (PMID 34645898, 2021). "In the early phase of the disease, beta-cell function is relatively well preserved and insulin secretion is increased as part of the compensatory requirement for higher insulin levels to overcome insulin resistance." (PMID 34879878, 2021).
Insulin resistance (continued). "For the insulin tolerance test (ITT), the mice in the HFHS/OP and HFHS/OR had higher fasting glucose levels and developed insulin resistance as shown by a slower decrease in blood glucose levels at 60 and 120 min after insulin injection compared to the CON." (PMID 34508150, 2021). "Insulin resistance implies failure of insulin to activate glucose uptake in muscle and adipose tissue and glycogen synthesis in liver and muscle, and to inhibit liver gluconeogenesis and adipose lipolysis." (PMID 34659123, 2021). "It has been noted in the literature that overexpression of PTP1B protein in the liver tissue leads to permanent switch-off of insulin signaling and therefore increase hyperglycemic index due to insulin resistance mechanism." (PMID 34093192, 2021). "Islet dysfunction, reduced insulin secretion, decreased glucose utilization, and insulin resistance found in type 2 diabetes are factors contributing to the onset and progression of hyperglycemia." (PMID 34203830, 2021). "Insulin resistance is a complicated pathophysiologic mechanism characterized by impaired insulin signaling in insulin-sensitive tissues." (PMID 34803675, 2021). "Over the past several decades, the study of proteins involved in the regulation of the insulin signaling pathway, and liver knockout mouse models in particular, have generated novel insights into the etiology and pathophysiology of hepatic insulin resistance." (PMID 33477364, 2021). "The results of this study show that the fasting blood glucose, serum insulin level, and insulin resistance index of the electroacupuncture group were higher than of the control group, with the difference being statistically significant (P < 0.05)." (PMID 33824679, 2021). "It has previously been shown that MANF triggers insulin resistance by enhancing the activity of phosphatidylinositol 5-phosphate 4-kinase type-2 beta (PIP4k2b, a kinase known to regulate insulin signaling) localized to the endoplasmic reticulum." (PMID 34220710, 2021). "At the same time, INS has a higher concentration in plasma and can lead to insulin resistance, hyperglycaemia, and hyperinsulinaemia." (PMID 33585429, 2021). "Insulin resistance is a very complex syndrome and IKKβ has been shown to regulate insulin resistance by directly interfering with the insulin signaling pathway." (PMID 34957242, 2021). "A key role in DM2 development has been attributed to insulin resistance (IR), that is, decreased sensitivity of target tissues to insulin action." (PMID 34557264, 2021). "An impaired response to insulin injection was observed in both male and female homozygous R165W-hMC4R mice measured at 17–18 and 27–28 weeks, indicative of insulin resistance." (PMID 33434184, 2021). "In insulin resistance, compensatory beta cell adaptation ensures increased insulin secretion, which is usually able to sustain normoglycemia for long periods of time." (PMID 34359828, 2021). "In obesity, the glucose transport and adipocyte metabolism are decreased despite high circulating levels of insulin, also known as insulin resistance." (PMID 34211985, 2021). "Insulin resistance and hyperinsulinemia can also lead to elevated blood pressure by leading to endothelial dysfunction through insulin-induced sympathetic excitation." (PMID 34070381, 2021). "TNF-α has a significant effect on the insulin signaling pathways and directly contributes to insulin resistance and T2DM." (PMID 34489979, 2021). "Contrarily, in patients with T2DM, insulin treatment was associated with higher fibrinogen and PAI-1 levels due to insulin resistance." (PMID 34072487, 2021). "In mice models, the pharmacological blockade of myostatin induces muscle mass gain and improves metabolic management of insulin, triglycerides, and circulating adiponectin in obese mice with insulin resistance." (PMID 34680417, 2021).